INS (insulin)
Diseases named in the same sentence as INS in open-access papers (continued):
Sharing a sentence is not in itself a finding about the gene and the disease.
type 1 diabetes (continued). "In patients newly diagnosed with type 1 diabetes, clinicians have three choices of basal insulin: NPH or one of two insulin analogs, glargine and detemir." (PMID 24653838, 2014). "The EGP was 10 ± 7 μmol·kg−1·min−1 in normal rats and 108 ± 9 μmol·kg−1·min−1 in diabetic rats during the hyperinsulin clamps, which suggested that insulin greatly suppressed the EGP in normal rats, while the effects were limited in the type 1 diabetes rats." (PMID 24772449, 2014). "Ward and his coworkers used the glucagon to prevent hypoglycemia in type 1 diabetes, where the fading memory proportional derivative (FMPD) algorithm was used to design the subcutaneous insulin and glucagon infusion rates." (PMID 24260042, 2013). "Diabetes mellitus type I, insulin dependent diabetes mellitus (IDDM), is an autoimmune disorder which leads to the destruction of insulin-producing pancreatic islets." (PMID 29470733, 2013). "Whereas type 2 diabetic rats and humans show slightly increased plasma levels of insulin, combined with clearly decreased melatonin levels, the situation in streptozotocin (STZ)-induced type 1 diabetic rats is completely different." (PMID 23535335, 2013). "In the rat model of type 1 diabetes, with chemically ablated β-cells due to STZ treatment, melatonin levels were strongly increased, whereas plasma insulin concentrations were generally below detection limit." (PMID 23535335, 2013). "GLP-1 analogues, in addition to their insulin-tropic action, have beneficial effects in protecting pancreatic β-cell function, in suppressing glucagon secretion and in delaying gastric emptying, all characteristics which could be beneficial for the management of type 1 diabetes." (PMID 23806096, 2013). "T1D, also known as insulin-dependent diabetes mellitus (IDDM), results from the destruction of insulin-producing β cells in the pancreatic islets and has been identified as a T cell-mediated autoimmune disease." (PMID 23727938, 2013). "Modern type 1 diabetes (T1DM) treatment is based on patient education, active self-care and multiple-dose insulin using new technologies." (PMID 23805322, 2013). "Basal–bolus insulin therapy is the gold-standard treatment in patients with type 1 diabetes (T1D)." (PMID 23448369, 2013). "In addition, higher-level expression of genes involved in insulin sensitivity, erythropoiesis, hemangioblast generation, and cellular redox control was evident in spleens of cured mice, indicating their possible contribution to protection against type 1 diabetes." (PMID 23383062, 2013). "Conversely, another intervention study in subjects with new onset type 1 diabetes reported that a combination therapy of cyclosporine and MTX induced a temporary remission of the disease with a decrease of the required insulin doses." (PMID 22778921, 2012). "The Hyperinsulinemia/IR factor has correlated directly with insulin daily dose and inversely with HDL-cholesterol constantly in all five groups of individuals with type 1 diabetes." (PMID 23270560, 2012). "In the case of type 1 diabetes, the rationale for administering TNF is that insulin-autoreactive T cells bear several intracellular signaling defects that make them selectively vulnerable to death upon exposure to TNF." (PMID 22905105, 2012). "β-cells are the focal point in both Type I Diabetes Mellitus (T1DM) and T2DM, because of their capacity to produce and secrete insulin." (PMID 23110768, 2012). "In type 1 diabetes (T1D), CD8+ cytotoxic T lymphocytes, in conjunction with CD4+ T helper cells, destroy the insulin-producing β cells within the pancreatic islets of Langerhans." (PMID 22693523, 2012). "However, previous studies have shown positive correlations between amylase secretion and circulating C-peptide or 24-hr urinary C-peptide excretion in diabetic patients, principally in type 1 diabetes, suggesting that low circulating amylase may reflect low insulin secretion." (PMID 21496338, 2011).
type 1 diabetes (continued). "Children with type 1 diabetes (DM1) often use three daily (TID) injections with intermediate acting insulin at breakfast and bedtime, and rapid acting insulin at breakfast and dinner." (PMID 22067102, 2011). "This study suggests that for individuals with type 1 diabetes and A1c above 8%, CGM and SMBG with intensive insulin therapy is a cost-effective alternative to SMBG alone with intensive insulin therapy." (PMID 21917132, 2011). "Such a study was performed in subjects with type 1 diabetes who underwent 24-h glucose-clamp analyses with insulin detemir (n = 18), insulin glargine (n = 16) or NPH insulin (n = 17)." (PMID 20618882, 2010). "When genetically linked to the N-terminus of insulin in E. coli, the bacterial synthesized INS-RTB fusion protein enhanced immunological suppression of pancreatic islet inflammation (insulitis), which is critical for prevention of Type 1 diabetes onset." (PMID 22069653, 2010). "Type 1 diabetes (T1D) is a multifactorial autoimmune disorder where interaction and integration of immune response genes along with environmental factors play a role in autoimmune destruction of the insulin producing Pancreatic Beta cells." (PMID 19956544, 2009). "Type I diabetes (TID) is an autoimmune disease, resulting from destruction of the insulin-producing β-cells in the islets of Langerhans by autoreactive T cells." (PMID 18793419, 2008). "Thus in typical casesof the insulin therapy, according to blood tests, three or four times of insulininjections are subcutaneously carried out per day to compensate the lack ofendogenous insulin secretion for type 1 diabetes in order to suppress the riseof blood glucose levels." (PMID 18437199, 2008). "Only five type 1 diabetes loci with compelling evidence had been identified before the advent of GWA studies: the HLA class II genes on chromosome 6p21; the insulin gene (INS) on 11p15; CTLA4 on 2q33; PTPN22 on 1q13; and, IL2RA/CD25 on 10p15." (PMID 18045485, 2007). "Two multinational, openlabel, randomised-controlled trials (one for patients with type 1 diabetes, the other for type 2) compared new, longer-acting insulin glargine with standard NPH basal insulin." (PMID 17927832, 2007). "Unlike asthma, non‐adherence to insulin for children with Type 1 diabetes would generate immediate feedback." (PMID 41240349, 2026). "Clinical data support the idea that combining insulin with Lactobacillus probiotics significantly lowers HbA1c in patients with Type 1 diabetes mellitus (T1DM) as well as in T2DM patients who are not consuming any hypoglycemic drugs." (PMID 41431379, 2026). "Type 1 diabetes occurs when the immune system mistakenly attacks and damages the pancreas, resulting in a lack of insulin production." (PMID 41009460, 2025). "Although the long-term effects of insulin exposure on PCOS pathogenesis have not been extensively studied, type 1 diabetes patients can provide some insights due to their requirement for exogenous insulin administration." (PMID 40013621, 2025). "It normally occurs in patients with type 1 diabetes because of a lack of insulin, which forces the body to metabolize ketone bodies instead of glucose." (PMID 41020054, 2025). "Although the study controlled for this bias by excluding patients using insulin, it is possible that some participants without prior knowledge of the disease and diagnosed through laboratory measurements are individuals with type 1 diabetes." (PMID 39147370, 2025). "In conclusion, our findings suggest that although an RCD significantly reduces the total daily dose of insulin in individuals with type 1 diabetes, it does not lead to measurable improvements in insulin sensitivity or endothelial function compared to an SCD." (PMID 40045281, 2025). "Although a one-week RCD significantly lowered insulin requirements, it failed to enhance insulin sensitivity or endothelial function in adults with type 1 diabetes." (PMID 40045281, 2025).
type 1 diabetes (continued). "Thus, the objective of this trial was to compare glucose control during HCL insulin therapy with SMA (simplified meal announcement) vs CC in youth and young adults with type 1 diabetes using HCL insulin therapy." (PMID 39560745, 2025). "Initially diagnosed with Type 1 diabetes (T1D), she required low insulin doses and displayed negative autoimmune markers." (PMID 40486195, 2025). "Type 1 diabetes is recognized as a chronic disease with a presymptomatic phase that does not require insulin therapy and a clinical phase where insulin treatment becomes necessary." (PMID 40134221, 2025). "In general, people with type 1 diabetes with lower incomes often face numerous challenges that limit their opportunities to adopt technology, including access to insulin pump therapy and CGM systems, not to mention AID systems." (PMID 39653802, 2025). "It should be noted that because GLP-1RAs lower glucose by potentiating insulin secretion, they are not suitable for type 1 diabetes and cannot replace insulin therapy." (PMID 41573745, 2025). "Diabetes type I at first seems like a simple problem: the body does not produce insulin, so we supplement the insulin." (PMID 39609614, 2025). "By focusing exclusively on type 1 diabetes and incorporating multiple metrics, including HbA1c, hypoglycemia, coefficient of variation (CV), time in range (TIR), insulin dose, and body measurements, this review seeks to inform dietary guidelines for type 1 diabetes." (PMID 40641818, 2025). "We systematically searched Medline, Embase, and Cochrane Library up to 11 November 2024 for RCTs on dietary patterns and glucose control outcomes in type 1 diabetes, including HbA1c, time in range (TIR), coefficient of variation (CV), hypoglycemia, insulin dose, and anthropometric characteristics." (PMID 40641818, 2025). "Based on our experience, we suggest a two-step approach for monitoring and treating patients with early stage 3 type 1 diabetes: first, positioning CGM, and second, when TIR falls below 80%, considering the addition of an AHCLs, even if the patient has a low insulin requirement." (PMID 40529832, 2025). "Automated insulin delivery systems, which mainly utilize proportional-integral-derivative (PID) and model predictive control (MPC) models, have successfully transitioned from the research bench to becoming the standard of care for people with type 1 diabetes." (PMID 40861074, 2025). "Our group previously reported reduced insulin clearance in youth with stage 1 type 1 diabetes compared with non-diabetic control individuals in a cross-sectional analysis." (PMID 39560746, 2025). "SPIDDM/LADA is a subtype of type 1 diabetes characterized by the slow autoimmune destruction of pancreatic islet β cells, typically without requiring insulin at the time of diagnosis." (PMID 40650275, 2025). "Cord serum concentrations of IGF-I are increased in newborns of insulin-treated mothers (Type 1 diabetes [T1D] and Type 2 diabetes [T2D]) compared to nondiabetic controls." (PMID 41333061, 2025). "Effective management of insulin hypersensitivity is particularly critical in individuals with type 1 diabetes, who cannot be transitioned to non-insulin hypoglycemic agents." (PMID 40869188, 2025). "Type 1 diabetes mellitus (T1D) is a metabolic condition marked by decreased or absent insulin production, which raises blood glucose levels." (PMID 40299229, 2025). "From the application point of view, insulin-327 appears to be more appealing for type 1 diabetes, considering its lack of insulin." (PMID 41155876, 2025). "In type 1 diabetes, abatacept did not prevent glucose intolerance but helped maintain insulin secretion, indicating potential for immune modulation in beta-cell preservation." (PMID 40142915, 2025). "Many patients are initially misclassified as having type 1 diabetes and are started on insulin therapy without undergoing appropriate genetic evaluation." (PMID 41367630, 2025).
type 1 diabetes (continued). "The aim of the study is to determine the optimal bolus split for maintaining postprandial glycemia with a balanced mixed meal in adolescents with type 1 diabetes using non-automated insulin pumps and CGM." (PMID 41156539, 2025). "While insulin pumps and advanced hybrid closed-loop systems support flexible insulin dose adjustments in runners with type 1 diabetes (T1DM), they are not essential for participation in long-distance events such as marathons." (PMID 40217942, 2025). "Type 1 diabetes results from an autoimmune attack on pancreatic beta cells, culminating in a profound lack of insulin." (PMID 40569436, 2025). "Type 1 diabetes (T1D), also known as insulin-dependent diabetes, is a chronic condition where the pancreas produces little or no insulin, which cannot be prevented." (PMID 41019347, 2025). "Self-management of PA is often challenging for individuals with type 1 diabetes, no matter what type of insulin therapy they are using." (PMID 39653802, 2025). "In patients with type 1 diabetes, endogenous insulin production is virtually absent, as indicated by undetectable C-peptide levels, rendering them entirely dependent on exogenous insulin to prevent ketoacidosis." (PMID 40951123, 2025). "In the absence of routine autoantibody testing to confirm type 1 diabetes, the classification depended on clinical judgement, history of insulin dependency, age at diagnosis and provider documentation." (PMID 40951600, 2025). "suggests that although betatrophin levels are increased in patients with type 1 diabetes, its levels do not correlate with C-peptide levels, glycemic control, or insulin requirements." (PMID 40607224, 2025). "The main aim of this study is to compare glycemic control and treatment satisfaction among patients with type 1 diabetes using SAIPs, insulin pumps without sensors, and MDI." (PMID 41250728, 2025). "Recent technological advancements have significantly transformed diabetes management, notably through the development of automated insulin delivery (AID) systems designed to reduce disease burden and enhance glycemic control for individuals with type 1 diabetes." (PMID 40547532, 2025). "To determine whether reduced insulin signaling affects HNSCC tumor growth in vivo, we used a STZ-induced type I diabetes mouse model." (PMID 40371988, 2025). "Of the 217 children diagnosed with type 1 diabetes who did not have an insulin prescription, 131 had already been censored by July 2005 when the Swedish Prescribed Drug Register was initiated." (PMID 39694913, 2025). "Autoantibodies associated with type 1 diabetes (T1D), including glutamic acid decarboxylase (GAD), protein tyrosine phosphatase, zinc transporter 8, and insulin antibodies, were negative." (PMID 41137338, 2025). "Our trial suggests that although an RCD reduces TDDinsulin by 16% type 1 diabetes, it does not improve insulin sensitivity or endothelial function compared to an SCD." (PMID 40045281, 2025). "To further prove this theory, we should focus on the plasma TSA levels in patients with newly diagnosed type 1 diabetes who have not yet received insulin treatment in future research." (PMID 41301440, 2025). "Overall, 19,610 children in our cohort had a dispensed prescription of insulin, of whom 5.2% (1010) did not have type 1 diabetes according to our outcome definition." (PMID 39694913, 2025). "Participants with type 1 diabetes had lower glucose infusion rate (GIR) during the high-dose phase (61.9 ± 20.1 μmol/kgFFM/min and 87.7 ± 18.4 μmol/kgFFM/min respectively; p = 0.00001), indicating impaired insulin-stimulated glucose uptake by skeletal muscle." (PMID 41285865, 2025). "Type 1 diabetes mellitus (T1DM) is a chronic autoimmune disorder that affects millions of individuals worldwide, primarily characterized by the autoimmune destruction of pancreatic β cells, which produce insulin—a hormone essential for blood glucose regulation." (PMID 41295485, 2025).
type 1 diabetes (continued). "To identify type 1 diabetes patients, we used a literature-based method choosing insulin users who did not use any other glucose-lowering medications and were aged under 30 years." (PMID 39755842, 2025). "The comparative efficacy of automated insulin delivery (AID) systems and other treatment options for type 1 diabetes, accounting for the certainty of evidence (CoE), is unknown." (PMID 40270713, 2025). "Using the hyperinsulinemic-euglycemic clamp technique with glucose isotope, we demonstrated that participants with type 1 diabetes had considerable muscle (29% lower GIR), liver (64% higher EGP) and adipose tissue insulin resistance, and greater arterial stiffness, than control participants." (PMID 41285865, 2025). "A recent study of nPOD donors found enterovirus RNA in both insulin-positive cells and insulin-negative cells in some donors with type 1 diabetes, including immune cells in the pancreas using fluorescent in situ hybridisation." (PMID 40095061, 2025). "In type 1 diabetes patients, due to insufficient or absent insulin secretion, blood glucose levels are chronically elevated." (PMID 39149550, 2024). "In type 1 diabetes, the absolute lack of insulin increases hepatic gluconeogenic capacity and derepresses lipolysis and proteolysis, promoting unrestrained release of substrates for gluconeogenesis (and ketogenesis) and raising blood glucose." (PMID 38826340, 2024). "In this cohort study using Colorado’s All-Payer Claims Database, nonelderly insulin users with type 1 diabetes were analyzed from January 2019 to December 2020." (PMID 39141389, 2024). "The idea of adjunctive oral antidiabetic therapy with insulin therapy in people with type 1 diabetes is not new." (PMID 39598003, 2024). "In subjects without type 1 diabetes, insulin is secreted from the pancreas into the portal vein, where 50-80% of insulin is metabolized in the first hepatic pass." (PMID 39906033, 2024). "Type 1 diabetes, previously known as juvenile diabetes or insulin-dependent diabetes, is a chronic condition characterized by little to no natural insulin production by the pancreas." (PMID 39517861, 2024). "Type 1 diabetes (T1D) is a chronic autoimmune disease in which islet β cells are destroyed and is characterized by the lack of insulin." (PMID 38566992, 2024). "Insulin levels did not alter during the trial in either participants with type 1 diabetes (p=0.68) or healthy participants (p=0.19)." (PMID 38427076, 2024). "Type 1 diabetes (T1D) is a chronic condition where the body produces little or no insulin, a hormone required to regulate blood glucose levels." (PMID 39654139, 2024). "In experiments with mice with type 1 diabetes, the nanosystem rapidly released insulin and maintained normal blood sugar levels for up to 84 h with a single injection, without affecting the blood sugar levels of healthy mice." (PMID 38819767, 2024). "Type 1 diabetes is characterized by an entire lack of insulin secretion, necessitating the use of insulin replacements." (PMID 39055230, 2024). "In type 1 diabetes (T1DM), the beta-cells are unable to produce insulin, and exogenous insulin needs to be administered via injections or an insulin pump, where the miscalculation of dosage and amounts and types of carbohydrates consumed often leads to hyper- or hypoglycaemia." (PMID 38474713, 2024). "When DWP16001, an SGLT2 inhibitor, was supplied to dogs with type 1 diabetes, no adverse effects were observed, and it was confirmed that the administered insulin dose can be reduced in controlling blood glucose." (PMID 38686463, 2024). "Within Type 1 diabetes (T1D), beta cells within pancreatic islets undergo autoimmune destruction over an extended period, resulting in a complete lack of insulin." (PMID 39123252, 2024).